RN7SKP131 (RN7SK pseudogene 131)
Gene: Miscellaneous RNA gene on chromosome 22 (18,605,802 to 18,606,102, reverse strand). Ensembl gene ENSG00000222630.
Homologues: Orthologues: chimpanzee 7SK (99% identical), guinea pig 7SK (63% identical). Paralogues in human: RN7SKP63 (100% identical), RN7SKP221 (99% identical), 7SK (79% identical), RN7SKP71 (79% identical), RN7SKP78 (78% identical), RN7SKP176 (77% identical), RN7SKP203 (77% identical), RN7SKP189 (76% identical), RN7SKP9 (76% identical), RN7SKP50 (76% identical), RN7SKP20 (75% identical), RN7SKP79 (75% identical), and 284 more.